INS (insulin)
Diseases named in the same sentence as INS in open-access papers (continued):
Sharing a sentence is not in itself a finding about the gene and the disease.
Obesity (continued). "Mice with a disruption in the Scd1 gene have increased energy expenditure, reduced body adiposity, and increased insulin sensitivity, and are resistant to diet-induced obesity." (PMID 33198144, 2020). "There is evidence ALA enriched (Chia seed) or high polyunsaturated:monounsaturated fatty acid ratio diets improve insulin signaling and glucose handling in models of obesity or T1D." (PMID 32887376, 2020). "In obesity, there is compromised metabolic flexibility due to the deteriorated insulin-mediated substrate switching." (PMID 32340248, 2020). "We also found that RXRα S22 phosphorylation is promoted by insulin and upon re-feeding in brown adipose tissue in vivo, and that insulin-stimulated S22 phosphorylation of RXRα is dampened by diet-induced obesity." (PMID 32249683, 2020). "It is known that microvascular dysfunction is a frequent concomitant of obesity, which coincides with hypertension and decreased insulin sensitivity." (PMID 32359193, 2020). "These 5 candidate taxa represent the candidate microbial community that constitute an independent factor altering insulin clearance during diet-induced obesity." (PMID 32860984, 2020). "Postprandial free fatty acid (FFA) release is greater in abdominal than in lower body obesity, indicating a faster rate of lipolysis in the visceral adipocytes which are inherently resistant to the antilipolytic effect of insulin." (PMID 33088334, 2020). "We observed significant improvements in measures of obesity, as well as static and dynamic measures of glucose, insulin, C-peptide and HOMA." (PMID 32067166, 2020). "Several environmental factors can influence insulin sensitivity: obesity, ethnicity, sex, perinatal factors, puberty, sedentary lifestyle, and diet." (PMID 32481506, 2020). "In mouse models, various genetic manipulation approaches to attenuate insulin secretion protects the mice from diet-induced obesity, IR and hyperglycemia." (PMID 32630256, 2020). "The NTS-mediated glucose metabolism is likely mediated through SORT1 as evidenced by the fact that Nts KO and Sort1 KO mice show resistance to obesity and hepatic steatosis, and greater insulin sensitivity on a high fat diet as common phenotypes." (PMID 33384578, 2020). "Aerobic and anaerobic PA favor loss of weight, visceral and subcutaneous adiposity, and ameliorates insulin sensitivity in subjects with obesity." (PMID 32390939, 2020). "Putting these studies together, it seems that the current study adds new insight into the effect of obesity and related abnormalities on regulating insulin signaling and hepatokine secretion in liver cells." (PMID 32322309, 2020). "Adipolin (CTRP12) is an insulin-sensitizing adipokine that is abundantly produced by AT and whose expression levels decrease in rodent models of obesity." (PMID 33282920, 2020). "Bariatric surgery results in a significant reduction in body mass index, in total daily insulin requirements and in co-morbidities related to obesity." (PMID 33071965, 2020). "In males, variables characterizing obesity status, insulin sensitivity, atherogenic dyslipidemia, uric acid, adiponectin, a soluble receptor for advanced glycation end-products, and leukocyte counts showed worsening trends across BP categories." (PMID 32455627, 2020). "Hepatic expression of miR-125a was recently revealed to be declined in models of mice obesity, while its overexpression promoted increase of insulin sensitivity and reduction of hepatic steatosis due to downregulating ELOVL fatty acid elongase 6 (Elovl6)." (PMID 32962281, 2020). "From these, we observed that genes involved in obesity and insulin pathways were upregulated after surgery." (PMID 32599690, 2020). "Insulin-stimulated glucose uptake by skeletal muscle and adipocytes becomes diminished in conditions of obesity, while physical exercise has beneficial effects on insulin sensitivity and glycemic control." (PMID 32867058, 2020).
Obesity (continued). "In addition to bringing the physical changes, obesity also causes considerable obesity-related inflammation and metabolic disorders, including dysfunction of adipose tissue and insulin resistance in key metabolic organs and insufficient secretion of insulin by the pancreas." (PMID 33015067, 2020). "Several factors increase the likelihood of becoming insulin resistant, including obesity, especially abdominal obesity, and physical inactivity." (PMID 33376604, 2020). "It is known that insulin signalling via AKT in models of obesity differs qualitatively in liver and kidney." (PMID 32971872, 2020). "Shikonin, a natural plant pigment, is known to have anti-obesity activity and to improve insulin sensitivity." (PMID 32316687, 2020). "It has been established that obesity often raises the blood levels of insulin and insulin-like growth factors, for as BMI increases there is also a direct increase in circulating insulin levels." (PMID 32742493, 2020). "Moreover, the consumption of yogurt and other dairy products has been shown to be associated with a high diet quality, a decreased risk of weight gain and obesity, as well as decreased risk of cardiovascular diseases, and it may contribute to a healthier insulin profile in adults." (PMID 32121167, 2020). "In men, similar to the sex-combined results, IMTmean was positively genetically correlated with the CHARGE IMTmean meta-analyses, total obesity, fasting glucose, and fasting insulin." (PMID 31801372, 2020). "Insulin is primarily a fat storage hormone and higher levels of insulin is a postulated reason for obesity (as per the carbohydrate-insulin model of obesity).“Safe” here means storage without inducing insulin resistance." (PMID 32582754, 2020). "JNK and NF-κB pathways in adipocytes and macrophages, activated in response to obesity-induced stimuli, directly inhibit insulin response." (PMID 32471061, 2020). "While many studies have focused on mechanisms triggering insulin secretion during obesity, the triggers for changes in insulin clearance during obesity are less defined." (PMID 32860984, 2020). "GO and KEGG analyses have shown that downregulated DEmRNAs in GSE104674 and GSE133099 were associated with obesity- and T2DM-related biological pathways, such as lipid metabolism, AMPK signaling, and insulin resistance." (PMID 32337289, 2020). "These solid results indicate that PLT has promising bioactivity in regulating obesity, insulin sensitivity, hyperlipidemia and hepatic steatosis by maintaining the composition of the gut microbiota." (PMID 33302947, 2020). "This was evidenced by recent studies that revealed treatment with NAC improved plasma insulin levels, increased insulin sensitivity across multiple tissues and increased motor activity in murine models of obesity." (PMID 32903449, 2020). "The G-308A polymorphism was also found to be associated with insulin sensitivity and increased production of leptin, suggesting an impact of TNF-α gene on obesity and obesity-related health complications." (PMID 30900134, 2020). "These include Thymoquine (black seed oil) in combination with Omega-3 that was shown to protect against obesity induced oxidative stress, improve insulin sensitivity and convert white fat to beige fat in a murine model of obesity." (PMID 32708430, 2020). "On the other hand, long-term elevation of insulin level during obesity, prolongs obesity, creating a positive feedback loop and inflammation changes into the chronic form." (PMID 32290863, 2020). "The first patient; however, had a type II DM on insulin treatment with severe obesity, in other terms a patient with higher risks of infection." (PMID 32049780, 2020). "These mice are hyperglycemic, hyperinsulinemic, hyperlipidemic, and insulin resistant, which makes them suitable for evaluating the effects of various factors on obesity and hyperglycemia." (PMID 32093016, 2020).
Obesity (continued). "Long-term anterior pituitary hormone deficiency can lead to disorders of glucose and lipid metabolism, obesity with higher percentage of body fat and insulin resistance." (PMID 32328036, 2020). "In response to calorie restriction and exercise, gene expressions of IL-1β and NLRP3 are reduced in the subcutaneous fat of patients with obesity and type 2 diabetes, accompanied with improvement in insulin sensitivity." (PMID 32545355, 2020). "Individual #2, for whom overeating and obesity had been a constant concern since childhood, had normal fasting glucose and insulin levels, as well as a normal oral glucose tolerance test at the age of 19 years (BMI 34.1 kg/m2)." (PMID 33076953, 2020). "Obesity induces resistance to insulin and reduces the function of pancreatic beta cells, which secrete insulin." (PMID 33187189, 2020). "Among the genes, we highlighted the Irf5, which is negatively correlated with insulin sensitivity and obesity, and Alox5ap, which signals adipose tissue inflammation and lipid dysfunction in adipose tissue of obese mice." (PMID 32906847, 2020). "This review will focus on the role of c-Jun N-terminal kinase (JNK) in T2D, as it has been found that the activity of this kinase is elevated during obesity and diabetes and this kinase can induce insulin resistance and ß-cell dysfunction." (PMID 32183037, 2020). "Feeding the mice HFUT over 12 weeks or introducing HFUT only in the last 6 weeks after inducing obesity with HF had the same effect on fasting insulin." (PMID 32290353, 2020). "Vaspin is known mainly for its insulin-sensitizing effects in metabolic syndrome, including obesity." (PMID 33049941, 2020). "During early adipogenesis, chemerin promotes insulin sensitivity, but increased adipogenesis during obesity makes chemerin release proinflammatory cytokines." (PMID 32858998, 2020). "FGF-21 has multiple metabolic actions in animal models of obesity that include enhancing insulin sensitivity, decreasing triglyceride concentrations, and causing weight loss." (PMID 32069846, 2020). "It is well established that obesity has a significant role in disturbing the metabolic regulation of glucose which is characterized by elevated insulin levels, glucose tolerance, and HOMA-IR." (PMID 32952453, 2020). "The relevance between obesity and β cell dysfunction is a fundamental research topic for the development of new therapies increasing insulin secretion and optimizing metabolism of T2D patients." (PMID 32286278, 2020). "Vice-versa, transplantation of Gps2-overexpressing bone marrow into two mouse models of obesity reduced inflammation and improved insulin sensitivity in recipient mice." (PMID 33117357, 2020). "These macrophage populations express high levels of pro-inflammatory cytokines such as IL1β and TNF, and previous studies have shown that deficiency in TNF as well as TNF neutralization can improve glucose and insulin tolerance in mouse models of obesity." (PMID 33330676, 2020). "As many of these diabetic patients suffer from type 2 diabetes in particular, we have recently identified that insulin dysregulation complicated by obesity significantly increased the propensity toward developing AF." (PMID 32903422, 2020). "Among the various models of inducing obesity in animals, the high-fat diet (HFD)-induced obesity model alters diverse biochemical factors, such as insulin, eventually leading to abnormal lipid metabolism." (PMID 33003339, 2020). "Knockdown of NNMT has been reported to have protective effects against diet-induced obesity, including lowering fat mass, serum triglycerides, free fatty acids, as well as increasing insulin sensitivity in mice with elevated energy consumption." (PMID 32895402, 2020). "The expansion of adipose tissue with the development of obesity occurs due to a combination of adipogenesis and lipogenesis, processes that are regulated by insulin/IR signaling." (PMID 33604295, 2020).
Obesity (continued). "For instance, the constitutive expression of XBP1 in POMC neurons was shown to protect the neurons against diet-induced obesity and also improved insulin sensitivity." (PMID 33329397, 2020). "Adiponectin is an insulin-sensitizing and anti-inflammatory molecule that is intensively studied in the context of obesity and obesity-related pathologies." (PMID 32937899, 2020). "Fecal microbiota transplants from healthy individuals into those with obesity and metabolic syndrome increased insulin sensitivity over a 6-week follow-up period." (PMID 33287442, 2020). "In contrast, plasma adiponectin shows an inverse correlation with body fat content, such that its level decreases in obesity; moreover, with regard to insulin sensitivity, a positive correlation has been found." (PMID 32325640, 2020). "The clinical significance of serum leptin and insulin levels in obesity has also been reported in the literature because of the positive correlation with an increase in body weight and fat mass." (PMID 33218042, 2020). "Treatment with these compounds can normalize insulin actions in obese mice as well as humans with obesity." (PMID 33066035, 2020). "Maternal risk factors, such as obesity, previous GDM, and family history, were significantly more prevalent in the insulin-treated group." (PMID 32987806, 2020). "Gene Ontology (GO) enrichment analysis showed that 13 genes were significantly involved with the onset of obesity and insulin-related pathways (p-value < 0.05)." (PMID 32599690, 2020). "Increased plasma LPS and LBP levels in subjects with obesity and T2D negatively correlated with muscle insulin sensitivity as well as reduced incidence of heart disease and T2D in subjects with TLR4 gene polymorphisms." (PMID 32295104, 2020). "Many studies have shown that catechins can be effective in controlling hyperglycemia and diabetic complications by improving insulin sensitivity and reducing dyslipidemia and obesity." (PMID 32781739, 2020). "Increased insulin secretion promotes adipogenesis by stimulating the activity of adipose tissue lipoprotein lipase resulting in weight gain and obesity." (PMID 32272767, 2020). "This elegant in vivo work demonstrated that in mice with diet-induced obesity, exogenous adropin causes an increase of IRS1, IRS2, and AKT phosphorylation suggesting that adropin increases hepatic insulin sensitivity." (PMID 32012786, 2020). "KATP channel activators can partially suppress insulin secretion, are approved for the treatment of hyperinsulinemia, and would be useful to reduce the contribution of hyperinsulinemia to hyperphagia and obesity." (PMID 32326226, 2020). "The present results first reported impaired insulin secretion and glucose disposal due to lipotoxicity and inflammation in the β-islets along rapid bodyweight gain and obesity development in broiler breeder hens provided with Ad-feed intake." (PMID 33114772, 2020). "As a consequence of tissue desensitization to the action of insulin, IR occurs in peripheral tissues in patients with diabetes and obesity and has recently been shown to develop in AD brains." (PMID 32829453, 2020). "As elevated concentrations of both LCSFAs and ω6-PUFAs correlate with metabolic alterations and impaired insulin action in obesity, we further investigated hypothalamic mitochondrial protein homeostasis, which is under the control of insulin." (PMID 32456175, 2020). "We describe the molecular basis of these undesired insulin actions and consequences of hyperinsulinemia for health-relevant endpoints, such as obesity or cardiovascular diseases." (PMID 32819363, 2020). "It has been also suggested that increased circulating irisin in obesity is a compensatory response to obesity-induced disturbed metabolism, such as decreased insulin level." (PMID 32917052, 2020).
Obesity (continued). "By activating AMPK, the master regulator of energy homeostasis, G. lucidum not only ameliorated obesity, but also improved overall systemic metabolism, including peripheral insulin sensitivity." (PMID 33142995, 2020). "Normally, the decrease in insulin sensitivity induced by obesity is compensated for by increasing insulin secretion to maintain normal glucose tolerance." (PMID 32239263, 2020). "Both obese Caucasian men and women are resistant to insulin’s antilipolytic action, suggesting a sex/race intersection in the effect of obesity on insulin’s action." (PMID 32354182, 2020). "The common biological mechanisms involved in obesity and neurodegenerative/neurodevelopmental diseases are insulin resistance, pro-inflammatory cytokines, and oxidative damage, among others, leading to impaired brain development or cell death." (PMID 32982666, 2020). "We have recently shown that CST improves insulin sensitivity by inhibiting obesity-induced inflammation and macrophage infiltration in the liver and by suppressing glucose production in hepatocyte." (PMID 32180905, 2020). "Male castration has previously been shown to lead to obesity and decreased insulin sensitivity in adult Göttingen minipigs." (PMID 32502216, 2020). "This condition includes changes in thyroid and insulin function and the development of comorbidities in early life, making obesity an important public health problem." (PMID 32481623, 2020). "In response to insulin-resistant states, such as puberty, pregnancy and obesity, healthy human pancreatic β-cells can secrete up to four to five times more insulin, which maintains a normal glucose level." (PMID 33261162, 2020). "Significant positive genetic correlations were observed between IMTmean and total obesity (BMI), T2D, fasting glucose, and insulin." (PMID 31801372, 2020). "The treatment of diet based on saturated fatty acids exhibit the typical phenotypes of HFD-induced obesity, while the treatment of diet containing polyunsaturated ω-3 fatty acid show some beneficial effects on the body position and insulin action." (PMID 32948162, 2020). "Unlike in the healthy rodents on LCDs who reproducibly have lower fasted insulin, only one study using a mouse model of obesity (ob/ob), had decreased fasted insulin as compared to chow fed mice." (PMID 33187118, 2020). "The increased mitochondrial metabolism, combined with induced generation of healthy adipocytes, preserves insulin sensitivity, despite obesity." (PMID 32193374, 2020). "African American women possess lower cardiorespiratory fitness and a higher prevalence of obesity and insulin resistance compared to their white counterparts and also tend to be less physically active." (PMID 32974034, 2020). "It has been shown that pemafibrate suppresses diet-induced obesity in mice and improves their obesity-related metabolic abnormalities including glucose, insulin and TG levels." (PMID 32979918, 2020). "To assess the effect of obesity and T2D on cardiac insulin signaling, we used the diet-induced obesogenic T2D mouse model with animals receiving a high-fat high-sucrose diet (HFHSD) for 16 weeks, as previously validated by our group." (PMID 33258101, 2020). "For example, several immunocompromised mouse models (NOD and SCID mice) have been found to be resistant to the development of obesity and insulin resistance when fed high fat diet." (PMID 33584724, 2020). "In the context of obesity, adipocytes become hypertrophic and reduce their production and release of the insulin-sensitizing factor adiponectin." (PMID 32408016, 2020). "Overall, these results showed that adropin improves insulin sensitivity and glucose and lipid metabolism in obesity." (PMID 32012786, 2020). "Such macrophage polarization supports the classification of obesity as a chronic pro-inflammatory disease leading to metabolic dysfunctions, including insulin resistance." (PMID 33317011, 2020).